SPANXN1 (SPANX family member N1)
Synonyms: SPANX-N1; CT11.6
Tractability: No criterion of Open Targets' tractability assessment is met for any kind of drug.
Gene: Protein-coding gene on chromosome X (145,247,503 to 145,256,208, forward strand). Ensembl gene ENSG00000203923.
Homologues: Orthologues: chimpanzee SPANXN1 (99% identical). Paralogues in human: SPANXN5 (86% identical), SPANXN2 (74% identical), SPANXN3 (74% identical), SPANXN4 (53% identical).
Diseases named in the same sentence as SPANXN1 in open-access papers:
SPANXN1 is named in the same sentence as 2 diseases in open-access papers, as found by Europe PMC text mining. Sharing a sentence is not in itself a finding about the gene and the disease.
SPANXN1 shares sentences with these, for which no sentence is quoted: cancer (1 paper); schizophrenia (1).